VIM (vimentin)
Diseases named in the same sentence as VIM in open-access papers (continued):
Sharing a sentence is not in itself a finding about the gene and the disease.
cancer (continued). "The expression of E-cadherin and vimentin are the main hallmarks of EMT during cancer metastasis." (PMID 34577566, 2021). "Furthermore, the expression of vimentin (VIM), a mesenchymal protein that is strongly expressed in malignant cancers, was similar to the FN pattern." (PMID 33917452, 2021). "It has been reported that vimentin could be a potential molecular target for cancer therapy, which opens up a new path for the development of promising therapeutic drugs." (PMID 34830378, 2021). "Indeed, vimentin was found to control the adhesion of breast and lung cancer cells by modulating the activity of focal adhesion kinase." (PMID 33921783, 2021). "Vimentin, an intermediate filament (IF) is essential for angiogenesis and cancer growth." (PMID 34946778, 2021). "Our platform was proven to have high specificity and sensitivity for the detection of rare CTCs in the blood sample of HCC patients, and further comparison was carried out with the separation ability of EpCAM and Vimentin, which are universal types of pan-cancer." (PMID 33726759, 2021). "Our findings reveal the inhibitory effect of IGFBP-3 on cancer migration and metastasis by negatively regulating vimentin expression through ubiquitin-mediated proteasome degradation through the cooperation with the E3 ligase FBXL14 in aerodigestive tract cancer cells." (PMID 33801272, 2021). "Interestingly, the effects of added recombinant vimentin were again stronger in the MCF-7 cancer cells compared to the MCF-10a cells." (PMID 34299089, 2021). "Indeed, Vimentin plays a crucial role in nurturing the metastatic cancer cells and aiding their escape from the cytotoxic effects of chemotherapeutic agents, thus fostering drug resistance." (PMID 33500399, 2021). "It is therefore tempting to suggest that mechanisms underlying the 5-AZA effects not only control the induction of apoptotic features, but may also reduce the risk of metastasis of ALL cancer cells through downregulation of SNAIL1 and vimentin transcripts." (PMID 34837933, 2021). "In addition, it has been shown that knockdown of HGBC reduces cell migration, expression of vimentin and N-cadherin, and decreased metastatic liver nodules after injection of cancer cells in the spleen in mice." (PMID 34575316, 2021). "Furthermore, as one of the primary cytoskeletal components in mesenchymal cells, vimentin, whose concentration has been shown to increase during EMT, is closely associated with the differentiation, metastasis, and invasion of cancer cells." (PMID 34239351, 2021). "Taken together, these results suggested that IGFBP-3 internalizes and makes a complex formation with vimentin and FBXL14, thereby causing polyubiquitination and proteasomal degradation of vimentin and suppressing EMT-associated metastatic phenotypes of cancer cells." (PMID 33801272, 2021). "This study examined the effect of ATD on TGF-β1-induced expression of cancer cell progression associated proteins, and the results showed TGF-β1 promoted the expression of integrin α3, N-cadherin, vimentin, and MMP2, while TGF-β1 cotreated with ATD inhibited such expression." (PMID 34572296, 2021). "eUnaG may help to resolve ultrastructures and dynamics of vimentin at the aggresome in vivo, thereby revealing the organismal implications in aging and cancer." (PMID 33959634, 2021). "Besides, MTHFD2 knockdown diminished N‐cadherin and vimentin expression in LUAD cells since EMT is a fundamental property for cancer metastasis." (PMID 34121323, 2021). "It was described that CAFs activated through paracrine Hedgehog signaling in turn induce the Snail transcription factor in PDAC cells, thereby leading to EMT in the cancer cells (as indicated by vimentin upregulation and E-cadherin downregulation) and enhancing their invasive capacity." (PMID 34646829, 2021). "Vimentin and N-cadherin are mesenchymal markers indicating the initiation of cancer metastasis." (PMID 33098307, 2021).
cancer (continued). "Vimentin, a major constituent of intermediate filament proteins whose expression is significantly elevated in multiple aggressive cancers including TNBC, participates in EMT process with a series of pro-metastasis effects, e.g. cytoskeleton reprogramming and stemness sustentation." (PMID 33530981, 2021). "Besides, EMT is one of the essential steps for initiating cancer metastasis, and E-cadherin, N-cadherin, and vimentin are considered as important EMT-related proteins." (PMID 34124072, 2021). "CTCs with the expression of mesenchymal markers, like TWIST1, SNAIL1, or vimentin were more likely to be identified in patients with advanced cancer compared to those with early-stage cancer, suggesting the potential role in metastatic dissemination and disease progression." (PMID 34150608, 2021). "The absence of viable Vim−/− clones may suggest a critical role of vimentin in this particular cancer type." (PMID 34305581, 2021). "A growing body of evidence suggests that vimentin may be a promising molecular target for novel therapies against many types of cancer." (PMID 33670389, 2021). "In addition, miR-384 overexpression reduced the EMT activity in cells, another major characteristic during cancer progression, presenting by decreased Vimentin while increased E-cadherin." (PMID 33911345, 2021). "Vimentin is not only expressed in cancer cells of different tissue origin, it is also expressed in endothelial cells and has been increasingly shown to be involved in vasculature branching through several mechanisms including the regulation of Notch signalling pathways." (PMID 34203746, 2021). "Extracellular vimentin was shown previously to be involved in cancer-cell invasion." (PMID 34299089, 2021). "In cancer invasion, PLK1 is also associated with phosphorylation of vimentin at Ser83, which regulates cell surface β1-integrin, though its regulatory mechanism in metastasis remains unclear." (PMID 33963314, 2021). "Consistent with a previous study on uterine cervical cancer, the correlation between MACC1 and the EMT-related proteins, vimentin and E-cadherin, observed in this study indicate the association between MACC1 and EMT in NPC, thus adding NPC to the list of cancers previously reported to involve EMT." (PMID 33854976, 2021). "The cells expressing S339E forming IFs represented ≈15% of all cells, while 53% of cells expressing S339A formed IFs bundles, indicating that phosphorylation of vimentin leads to disassembly of IFs to increase motility of cancer cells through lamellipodia formation." (PMID 33963314, 2021). "We have focused on citrullinated vimentin and α-enolase as attractive cancer vaccine targets." (PMID 33859638, 2021). "In addition, it is reported that vimentin protects the cancer cells from the internal stress of misfolded proteins by directly binding to stress granules and aggresomes, supporting their subsequent destruction." (PMID 34638469, 2021). "Similar to the cytokine profiling results, most of the cancer‐associated proteins, such as ANGPTL4, KLK5, GAL3, VIM, HERs, CAPG, HO, CTSD, and AFP were produced at higher levels on the aged matrix, but were reduced to young matrix levels after LOX siRNA treatment." (PMID 34617419, 2021). "In addition, we observed that the LMW compounds concomitantly reduced the expression of mesenchymal markers vimentin and N-cadherin, decreased the clonogenic potential of aggressive cancer cells and induced changes in the actin cytoskeleton." (PMID 33567533, 2021). "Therefore, it is also vital to study the role of surface vimentin in viral and bacterial infections in the context of cancer progression." (PMID 34299089, 2021).
cancer (continued). "Through suppressing the key of enzymes of glycolysis LDHA and mitochondrial metabolism PDK1, induced by TGF-β1, the mesenchymal subtype markers N-cadherin and Vimentin are negated, suggesting that the metabolic reprogramming is directly related to cancer metastasis." (PMID 34257808, 2021). "Suppression of vimentin expression was found to block the migration and adhesion of cancer cells." (PMID 33801272, 2021). "The results showed that the expression of Vimentin and N-cadherin were significantly higher in ccRCC cancer tissues than in paired normal tissues, whereas the expression of E-cadherin in ccRCC cancer tissues was significantly lower than in paired normal tissues." (PMID 34956878, 2021). "In CRC-LM samples, TGFBI could be detected frequently also in cancer cells (pan-cytokeratin-positive), although its expression remained predominant in stromal cells (vimentin-positive)." (PMID 33408771, 2021). "In addition, previous studies have reported that vimentin, which is a biomarker of epithelial to mesenchymal transition, is required for cancer stem cell metastasis." (PMID 34502264, 2021). "Because of the importance of Twist1 in metastasis, we also examined the expression of EMT markers E-Cadherin, N-Cadherin, and Vimentin in harmine-treated cancer cells and demonstrated that reduced Twist1 affects the Twist1-regulated downstream targets involved in EMT." (PMID 33626096, 2021). "In our study, we found that blocking TGF-β1 and vimentin deletion induced cancer cells to detach and survive, suggesting that PERK, PI3K/AKT, and ERBB2 may also be involved in the survival of detached cells through increasing the anoikis-independent process." (PMID 34830801, 2021). "Regarding vimentin phosphorylation, some sites favor IF assembly, whereas others promote disassembly, hence it is difficult to make general statements regarding the effect of its phosphorylation in cancer progression." (PMID 36046434, 2021). "A recent study showed that vimentin filaments could promote the extension of tubulin-based microtentacles, suggesting that a possible mechanism to facilitate cancer invasion was provided by the coordination of vimentin and microtubules." (PMID 33628783, 2021). "The action of the vimentin to maintain cell shape and cytoplasmic integrity and to stabilize cytoskeletal interactions makes it a pivotal player impacting the secretion, migration, and invasion properties of cancer cells." (PMID 34831282, 2021). "The expression of WT-1, vimentin, CycD1, and ER was variable in all carcinoma types." (PMID 35002543, 2021). "E-cadherin and vimentin are very important factors in EMT process of cancer development." (PMID 32148496, 2020). "High Vimentin expression represents a poor prognostic marker in cancer." (PMID 32183322, 2020). "At the molecular level, these substances reduce expression of the epithelial markers E-cadherin, HIF-1α, and/or TGF-β1 and increase expression of the mesenchymal markers vimentin and N-cadherin, which inhibit cancer cell migration and invasion, therefore downregulating the EMT process." (PMID 32377312, 2020). "This time point may not be the optimal one to measure BDNF dynamics in 40% O2 group but increased Vimentin and decreased E-Cadherin expression in cancer cell were already present to demonstrate a pick of undetected BDNF expression." (PMID 32183322, 2020). "The expression of vimentin promotes mesenchymal morphology of the metastatic cancer cells." (PMID 32751717, 2020). "Therefore, vimentin is considered as a potential indicator for cancer prognosis and therapeutic target." (PMID 31968004, 2020). "In contrast to the controls or cells treated with NSF-CM, the expression of the epithelial marker E-cadherin in the cancer cells significantly decreased upon treatment with H-CAFs, whereas the expression levels of the mesenchymal markers N-cadherin, vimentin, fibronectin, α-SMA, and Slug increased." (PMID 32792856, 2020).
cancer (continued). "Interestingly, VIM, besides being a key regulator of cell adhesion and cell–cell interactions, has a well-known role in the EMT process in many types of cancer, while IGFBP6 is particularly implicated in the IGF1-mediated EMT." (PMID 32878319, 2020). "Thus, an abnormally elevated expression of Vimentin is considered as a marker for enhanced invasive ability of cancer cells." (PMID 32194806, 2020). "For instance, the critical EMT-inducing transcription factor Twist1 is driven by hypoxia to translocate from cytoplasm into the nucleus of cancer cells, followed by upregulated expression of the mesenchymal protein, Vimentin and the essential endothelial specific adhesion molecule, VE-cadherin." (PMID 32599893, 2020). "Additionally, DHRS4-AS1 inhibited the expression of epithelial-mesenchymal transition (EMT)-related factors, N-cadherin, ZEB1, and Vimentin but increased E-cadherin expression in the cancer stem cell spheres." (PMID 33425890, 2020). "Indeed, both endogenously generated and manufactured anti-vimentin antibodies have been used as potential therapeutic tools, above all in cancer." (PMID 32630064, 2020). "A loss or a decrease in EpCAM expression and an increase in mesenchymal markers such as N-cadherin, vimentin, and podoplanin in cancer cells may accompany the EMT." (PMID 32071283, 2020). "Therefore, new approaches targeting vimentin constitute promising therapeutic venues for anti-cancer therapy." (PMID 31940801, 2020). "Next, as representative examples relevant to a large number of cancers associated with EMT, we examined VIM and MMP9 expression in more detail (assessed by individual RT-qPCR and immune-detection), which have also been examined in the context of EMT-related melanomagenesis." (PMID 32466621, 2020). "VIM SUMOylation in turn favors cell proliferation and motility, which could lead to an increase in cancer cell aggressiveness." (PMID 32047143, 2020). "Furthermore, Twist1 expression positively correlates with EMT genes (CDH1, OCLN, TJP1, CDH2, FN1, SNAI1 and VIM) in various cancers." (PMID 32337580, 2020). "Moreover, they induce the expression of vimentin, actually a mesenchymal protein, which is essential for the increased migratory properties of cancer cells." (PMID 32630033, 2020). "Vimentin, also an intermediate filament protein, is a cytoskeletal component of the mesenchymal cells and has been used as a biomarker for transition between epithelial and mesenchymal states in the development and metastasis of cancers." (PMID 32513981, 2020). "Vimentin is a type of intermediate filament protein that is up-regulated during epithelial-to-mesenchymal transition, a process that occurs during neural development, wound healing, and cancer metastasis." (PMID 32596263, 2020). "In addition, the level of VIM protein was also significantly increased in cancer cells after incubation with ELN protein and peptide compared to controls, indicating elastin proteins induced EMT in colon epithelial cancer cells." (PMID 32171282, 2020). "Taken together, hypomethylation of Sipa1 promoter-proximal elements by treating MCF7 cells with 5-Aza-CdR upregulated the expression of SIPA1 and vimentin, suppressed E-cadherin expression, and promoted the cancer cell migration, which might lead to EMT." (PMID 32193333, 2020). "Vimentin, one of the proteins expressed during the cell transition, plays a crucial role in embryonic development, wound healing, inflammation and regeneration, as well as in the oncogenic transformation and dissemination of a malignant tumor." (PMID 32933173, 2020). "EA extract also prevents the progression of epithelial-mesenchymal transition (EMT), an important event for cancer invasion and metastasis; this is accompanied by upregulations of E-cadherin and β-catenin, in addition to downregulations of vimentin and fascin, which are major markers of EMT." (PMID 32947764, 2020).
cancer (continued). "As evidenced by recent discoveries discussed in the following text, intermediate filaments, particularly vimentin, have increasing implications in cancer progression, cancer cell migration, and invasion, and there is an intensified need for specific targeting of vimentin." (PMID 31940801, 2020). "Vimentin has also been targeted by nucleic acid aptamers, above all in anti-cancer strategies." (PMID 32630064, 2020). "Vimentin is a marker of epithelial-to-mesenchymal transition, a critical event in induction of cell motility involved in multiple biological processes including wound healing, cancer metastasis, and embryonic development." (PMID 32273567, 2020). "Consequently, the cancer cells from metastasis exhibited a significantly enhanced expression of mesenchymal marker vimentin, twist and zeb2 and a decrease of epithelial marker E-cadherin." (PMID 32225005, 2020). "Therefore, our assay specified an “epithelial” cancer cell presenting the phenotype CD45−/keratins+/vimentinlow/− and a “mesenchymal” cancer cell expressing the CD45−/keratins+/vimentin+ phenotype." (PMID 33322610, 2020). "Vimentin, E-cadherin, and N-cadherin are essential indicators of the cancer EMT process." (PMID 33094104, 2020). "Vimentin is an important indicator for cancer invasion and metastasis." (PMID 32920551, 2020). "Also, the transformed cancer cells have undergone EMT as shown through the loss of E-cadherin and acquisition of vimentin." (PMID 32268527, 2020). "In addition, certain strategies, including anti-vimentin antibodies or soluble vimentin, have been reported to reduce binding of bacterial microaggregates or viral particles to carcinoma cells." (PMID 32630064, 2020). "When aberrantly expressed in carcinoma cells, vimentin is seen as a marker of EMT." (PMID 32245446, 2020). "A further identified cell population showed high vimentin and SMA levels and might represent cancer-associated fibroblasts (CAFs)." (PMID 31297730, 2019). "Also, a significant difference was observed by comparing the number of vimentin-positive cancer cells between the G_2 and G_3 groups (p = 0.0040)." (PMID 31614564, 2019). "Therefore, the EMT process that is related to the expression of E-cadherin, vimentin which were generally used to demonstrate the ability of cancer cell metastasis and invasion." (PMID 30858762, 2019). "Researches revealed that the expression level of N-cadherin and Vimentin could indicate the capacity of invasion and metastasis of cancer cells." (PMID 31767833, 2019). "Vimentin was previously reported to be phosphorylated at Tyr53 and Tyr61 in cancer cells." (PMID 30696956, 2019). "Notably, RNF208 and Vimentin were inversely expressed in patients with luminal subtype cancer and TNBC tissues." (PMID 31862882, 2019). "Since N-cadherin and Vimentin have been proved usually positive in various cancer metastases, we speculated the downregulation of ATG5 might impact the HIF1α-induced metastasis ability of PC-3 cells." (PMID 31700698, 2019). "Vimentin also seems to have a role in regulating stemness of cancer cells." (PMID 31126068, 2019). "Vimentin is a major component of the intermediate filament cytoskeleton and is best known in cancer as a marker of cellular epithelial to mesenchymal transition (EMT), a phenomenon associated with cancer cell invasion and metastatic tumor spread." (PMID 30987208, 2019). "Throughout EMT, the cancer cells endure frequently molecular events, for instance, a decrease of the level of epithelial markers (E-cadherin, cytokeratins) and an increase of the level of mesenchymal markers (N-cadherin, vimentin)." (PMID 30691229, 2019). "In addition, vimentin is used as a canonical marker of epithelial-to-mesenchymal transition (EMT) and cancer-associated fibroblasts (CAFs)." (PMID 31827725, 2019).